TNF (tumor necrosis factor)
Diseases named in the same sentence as TNF in open-access papers (continued):
Sharing a sentence is not in itself a finding about the gene and the disease.
tumor (continued). "Meanwhile, severe pain is not only caused by the pain factos produced by tumor cells, such as prostaglandin, interleukin-1 (IL-1), and the tumor necrosis factor (TNF), but also caused by the tumor involvement in the periosteum, nerve, and soft tissue." (PMID 39036661, 2023). "Both IFNγ and TNFα promote M1 macrophage polarisation, and induction of M1 macrophages is associated with reduced tumour burden in mouse CRC." (PMID 37455828, 2023). "One strategy is to target the TNF signaling and autophagy pathways, which cause tumor cells to die as a result of the cytokines released by T cells." (PMID 38041084, 2023). "Previous studies have found that neutrophils in TME release factors associated with tumor proliferation and metastasis, such as tumor necrosis factor (TNF), vascular endothelial growth factor (VEGF), elastase, and matrix metalloproteinases." (PMID 37456236, 2023). "Nonetheless, a study of 83 HCC patients with early-stage HCC (TNM stage I) showed that patients with a higher TNF-α expression in tumor tissue had a lower risk of recurrence and mortality compared with those with a lower TNF-α expression." (PMID 37958479, 2023). "TNF-α, one of the inflammatory cytokines from the tumor microenvironment, is associated with metastasis and aggressiveness in various cancers, including TNBC." (PMID 37041137, 2023). "We found that the expression of CDKN2A was significantly associated with tumor immune-related pathways such as the TNFα signaling pathway via NFκB, IFN-α response, IFN-γ response, allograft rejection pathway, and inflammatory response." (PMID 36961395, 2023). "Using loss- and gain-of-function experiments, we show that ADAM2 functions as an oncogene by restraining interferon and TNF cytokine signaling causing reduced presentation of tumor-associated antigens." (PMID 37258521, 2023). "It causes tumor inflammation through macrophages and increases the expression of TNF-a and IL-6, and also increases angiogenesis with high expression of CD31, VEGFR2, and HIF1a." (PMID 37361568, 2023). "Tumor necrosis factor α secreted by tumor cells can cause significant damage to the digestive tract, leading to inflammation." (PMID 37365298, 2023). "Pro-inflammatory cytokines and chemokines, such as IL-6, IL-8, IL-1β, and TNF-α, can activate stromal cells, including CAFs and tumor-associated macrophages (TAMs)." (PMID 37760801, 2023). "The expression level of TNF was significantly higher in high-risk group and tumor tissue than that in low-risk group and normal tissue." (PMID 37704909, 2023). "Beyond certain tumour cell intrinsic changes, multiple microenvironmental factors including tumour associated macrophages, secreted molecules (IL-1, TNF-α) or hypoxia have been described to promote EMT47–49." (PMID 36774358, 2023). "TAMs secrete forceful proangiogenic factors such as VEGF and TNF-α, which facilitate tumor-associated angiogenesis and aid tumor cell proliferation, migration, and metastasis." (PMID 37046639, 2023). "TNF-α causes macrophage activation inducing the release of additional pro-inflammatory cytokines and enhancing their anti-tumor cytotoxic and pro-apoptotic activity." (PMID 37346794, 2023). "The initial response to the bacterial colonization of tumors is the secretion of the proinflammatory cytokine TNFα by innate immune cells, which causes a hemorrhage in the tumor and the formation of large necrotic regions." (PMID 36900277, 2023). "Tumor-associated MSCs induce angiogenesis through secretion of TNFα, vascular endothelial growth factor (VEGF), interferon (INF)γ, leukemia inhibitory factor (LIF), macrophage colony-stimulating factor (M-CSF) and endothelin secretion by tumor cells." (PMID 37046676, 2023). "As we have already indicated, tumor-infiltrating pDCs were significantly increased in the TME and were associated with tumor size and lymph node metastasis via the TNF-α/NF-κB/CXCR-4 pathway in OSCCs." (PMID 35740551, 2022).
tumor (continued). "Tumor necrosis factor has an effect on tumor-associated macrophages and cancer cells, thus affecting the prognosis of patients." (PMID 36419829, 2022). "This notion was further backed by the continuously increased expressions of IL2, TNFα/β and IFNγ in tumor-associated CD8+ T cell in BAY-I and BAY-I withdrawal groups." (PMID 35013322, 2022). "TNF-α promotes tumor cell survival through the induction of genes encoding NF-κB-dependent antiapoptotic molecules." (PMID 35493517, 2022). "TNF-α is the cytokine that most consistently associated with tumor cell killing through activation of the transcription factor NF-κB and subsequent production of IL-1β, IL-6, IL-8 and IL-17." (PMID 35493517, 2022). "Tumor-associated neutrophils (TANs) cause CD8 T-cell apoptosis through the tumor necrosis factor (TNF)-α pathway, contributing to the immunosuppressive response." (PMID 36119533, 2022). "Chronic inflammation can cause DNA damage and proinflammatory cytokines, including TNF, IL-1, and IL-6, and can augment tumor growth and metastasis." (PMID 36450739, 2022). "The development of tumors is promoted by cytokines G-CSF, IFNγ, TNFα, IL-10, and IL-12p70 released by neoplastic cells and tumor-associated macrophages (TAM)." (PMID 35463072, 2022). "TMVs help tumor cells evade by exposing FasL proteins, tumor necrosis factor (TNF)-associated regulatory ligands, etc., to induce apoptosis in CD8+ T cells’ immune response." (PMID 35890175, 2022). "Rodent tumor models shown evidence that increased production of systemic inflammatory cytokines such as TNF-α, IL-1, and IL-6 was associated development of cancer cachexia and weight loss." (PMID 35538112, 2022). "Tumor development in this murine model was closely associated with the release of different proinflammatory and protumorigenic cytokines such as TNFα and IL6." (PMID 35267563, 2022). "Chronic inflammation is closely related to tumor initiation and progression, and both interleukin-6 (IL-6) and tumor necrosis factor (TNF) are the important indicators of tumor-associated inflammation." (PMID 35889396, 2022). "Fn inoculation significantly increased the expression of genes encoding the proinflammatory cytokines TNF-α and IL-1β in the tumor xenografts and colon tissues." (PMID 36551597, 2022). "TNF-α is an endogenous tumor promoter, and tumor TNF-α production is linked to a poor prognosis, hormonal response, and cachexia." (PMID 36276107, 2022). "NETs-associated proteinases activate matrix metalloproteinases to induce tumor-associated macrophages, which stimulate the release of pro-inflammatory factors (i.e., IL-8, IL-1β, and TNF-α), eventually leading to immune escape and tumor metastasis." (PMID 36466888, 2022). "In HCC, tumor-associated macrophages (TAMs) can produce cytokines to sustain tumor growth (i.e., IL-1β, TNF, IL-6), promote neo-angiogenesis via the VEGF pathway, and induce cytokine-mediated immunosuppression (i.e., IL 10, TGF-β)." (PMID 36551635, 2022). "TNFα-induced expression of the IL-35 receptor IL12Rβ2 already on 4T1 mammary cancer cells in the primary tumor, rendered these cells more susceptible to the effects of IL-35 secreted from MAMs upon arrival at the lung metastatic site." (PMID 35418981, 2022). "The high expression of TGF-β, VEGFA, and CXCL10 and the low expression of TNF-α indicated the tumor-supporting effect of GAMs in high risk score group." (PMID 36159780, 2022). "TNF-α has been implicated in both mediating potent antiviral effects and the cytotoxicity of tumor cells." (PMID 36139433, 2022). "TNF-α (tumor necrosis factor–α) is a cytokine associated with systemic inflammation, immune regulation, inhibition of tumor cell growth, and rejection of organ transplantation." (PMID 35559267, 2022). "T cells exhaustion, defined by the progressive loss of effector function after persistent infection or tumor antigens, lose the ability to produce cytokines, such as IFNγ, TNFα, and IL-2." (PMID 36050760, 2022).
tumor (continued). "Angiogenic cytokines released by tumor-associated DCs, including VEGF, TGF-β, TNF-α, IL-8, and osteopontin, directly contribute to tumor angiogenesis." (PMID 36419156, 2022). "In a 2020 article, it was reported that TNF-α can be used as a prognostic indicator, while various ILs (IL-2, IL-1β, and IL-6) were also discovered to be linked to tumor prognosis." (PMID 35677632, 2022). "Meanwhile, tumor-associated macrophages (TAM) type 2 that infiltrate the tumor microenvironment (TME) promote tumor necrosis factor-α (TNF-α) and further induce EMT in HCC." (PMID 36358885, 2022). "Both IL-6 and TNF-α are associated with tumor development and metastasis, and the inhibition of tumor growth suppressors in people with cancer." (PMID 35699799, 2022). "Th1 cytokines such as interferon γ (IFNγ), TNFα, or granulocyte/monocyte-colony-stimulating factor (GM-CSF) are implicated in tumor immunosurveillance and regulate cytotoxic activity." (PMID 36614001, 2022). "There were 48 intersected targets such as EGFR, AKT1, and TNF that were associated with patients’ outcomes by the univariate Cox analysis, and most of them had increased expression in the tumor as compared to normal tissues." (PMID 35873484, 2022). "Angiograms taken before and after TNF-based ILP showed that tumor-associated vessels were specifically affected, while normal vessels remained intact." (PMID 36297598, 2022). "A genetic relationship between the TNF polymorphisms and the risk of BC and tumor grade at presentation was observed." (PMID 36140470, 2022). "On the one hand, pDNA encodes TNFα, which inhibits tumor growth; on the other hand, the membrane penetrability of the SWNTs increases the damage to tumor cells." (PMID 34994069, 2022). "CXCR5+CD8 T cells from human peripheral blood mononuclear cells, tumor tissues and tumor associated lymph nodes upregulate effector molecules such as IFNγ, TNFα, granzyme B, and perforin compared to CXCR5−CD8 T cells." (PMID 36314014, 2022). "Multiple cytokines and chemokines, including CXCL12, CXCL16, interleukin (IL)-1β, IL-6, IL-34, macrophage colony-stimulating factor (M-CSF), and tumor necrosis factor-α (TNF-α), are also associated with tumor progression and hearing disturbance." (PMID 35628268, 2022). "MPT-PE activated M1-macrophages inhibit OS growth and this anti-tumour activity was partly associated with the release of TNF-α and IL1-β." (PMID 35990515, 2022). "The plasma concentration of proinflammatory cytokines, such as IL-1β, TNF-α, and IL-6, increases in several types of cancer due to the sustained inflammatory environment caused by the tumor and its stroma." (PMID 36072935, 2022). "TNFα is a central pro-inflammatory cytokine which is secreted with a series of inflammatory factors and cytokines by tumor-associated macrophages in the tumor microenvironment." (PMID 35056404, 2022). "Th1 cytokines, such as IL‐1β, IL‐2, IL‐12, IL‐18, TNFα, and IFNγ, are associated with proinflammation, while Th2 cytokines, such as IL‐4, IL‐5, and TGFβ, play a suppressive role in the tumour immune microenvironment." (PMID 35430766, 2022). "One of the more identified pro-inflammatory factors associated with cancer is tumor necrosis factor (TNF), which is a cytokine that promotes tumorigenesis via stimulation of cancer cell growth, tumor angiogenesis, proliferation, invasion, and metastasis." (PMID 37990728, 2022). "Downregulation of UCK2 induced cell cycle arrest and activated the TNFα/NFκB signalling pathway-related senescence-associated secretory phenotype to modify the tumour microenvironment." (PMID 36447138, 2022).
tumor (continued). "This is in line with multiple reports demonstrating that disruption of TNFα or IL-1R/IL-1β signaling by either blocking antibodies or deficient mouse models improves the anti-tumor immune response in combination with 5-FU or ICB." (PMID 35634282, 2022). "Apigenin not only reduced the expression of different tumor-causing genes such as TNF-α, IL-6 and CD40, but also increased the activity of the tumor-suppressing STAT1 gene via IFN-γ gene inhibition." (PMID 35807549, 2022). "For example, cytokines in the TME, such as TNF-α, IL-6, and IL-8, are associated with angiogenesis and tumor metastasis, whereas IL-4, IL-13, and IL-10 are associated with immune response suppression." (PMID 35844605, 2022). "TNF-α acts on endothelial cells to increase vascular permeability and mediates hemorrhagic necrosis, which can eradicate the tumor mass by damaging tumor-associated vasculature." (PMID 36066630, 2022). "A few years later, the name Tumor Necrosis Factor was coined for a serum factor that caused the destruction of tumors in vivo and was also active against tumor cell lines in vitro." (PMID 36358688, 2022). "On the other hand, being characterized by the expression of inducible nitric oxide synthase (iNOS) and tumor necrosis factor α (TNFα), tumor-associated M1 macrophages (TAM1) are known to exhibit anti-cancer activity via proinflammatory immune responses." (PMID 35053375, 2022). "In the tumor microenvironment, pathogen-associated molecules, such as LPS, interferon-γ, granulocyte–macrophage colony stimulating factor, and tumor necrosis factor-α, can induce the polarization of M0 macrophages toward an M1 phenotype." (PMID 36056336, 2022). "The neutralization of TNF-α reduces the cytokines in serum, inhibiting invasive lesion progression and further decreasing the neutrophils associated with the tumor in vivo." (PMID 36146567, 2022). "Macrophage type 1 is associated with tumor elimination via mechanisms dependent on reactive oxygen species and reactive nitrogen species, as well as production of Interleukin-1β and tumor necrosis factor-alpha." (PMID 35883639, 2022). "TAMs from SphK2-deficient tumors displayed a pronounced anti-tumor phenotype, showing an increased expression of the pro-inflammatory markers/mediators such as NO, TNF-α, IL-12 and MHCII and a low expression of anti-inflammatory IL-10 and CD206." (PMID 35756630, 2022). "In myeloid cells, TNF leads to the generation of a tumor-associated macrophage phenotype, that is associated with immune escape and tumor promotion." (PMID 35844550, 2022). "While tumor necrosis factor alpha (TNF-α) is not only extensively involved in the inflammatory response, it is also associated with tumor progression." (PMID 36497451, 2022). "Subsequently, the NCA‐encapsulated TNF‐α was released, which caused serious inflammation of endothelial cells of tumor vascular, further inducing the blood vessel damage." (PMID 35246962, 2022). "In NB, tumor-associated macrophages produce IL-1β and tumor necrosis factor-α to regulate arginine metabolism and thus promote cell proliferation." (PMID 35493068, 2022). "TNF-α is a central pro-inflammatory cytokine which is secreted with series of inflammatory factors and cytokines by tumor-associated macrophages in the tumor microenvironment." (PMID 35208526, 2022). "Follow-up in vitro and in vivo experiments indeed indicated that TRAF2 deficiency sensitizes tumor cells for killing by TNF expressed by CD8+ T cells." (PMID 36011046, 2022). "TNF Superfamily Member 12 (TNFSF12) belongs to the Tumor Necrosis Factor (TNF) protein family expressed in a range of organs, immune cell types, and tumor cells, which activates caspase 8 and caspase 9 and cause extrinsic and intrinsic apoptosis cascades." (PMID 35264191, 2022). "IFN and TNF signaling are associated with immune activation and anti-tumor responses in myeloid cells, suggesting that these cells promote adaptive immune responses in NP-treated mice." (PMID 36479083, 2022).
tumor (continued). "High doses of TNF caused major destruction of the vascular bed and induced haemorrhagic necrosis in both syngeneic and xenograft tumor models in mice." (PMID 35844550, 2022). "Pro-inflammatory cytokines are released by tumor-associated inflammatory cells, such as IL-1, IL-6, TNF, and VEGF, which further influences the tumor progression and metastasis." (PMID 35964079, 2022). "We also observed increases in several wasting-associated cytokines (i.e., IL-6 and TNF-α) in the serum of young and aged tumor-bearing mice, suggesting that systemic inflammation is a common feature of both models." (PMID 34874916, 2022). "Cells such as microglia and tumor-associated macrophages secrete cytokines, including TNF-α and IL-6, within the tumor microenvironment to further modulate NF-κB signaling." (PMID 35922651, 2022). "TNF was directly expressed in tumors by tumor cells but predominantly by tumor-associated macrophages (TAMs)." (PMID 36358688, 2022). "NK cells exert cytotoxic effects by secreting TNF, perforin, and granzyme, and tumor-associated NK cells have been found to associate with increased survival time in patients with CRC." (PMID 35401707, 2022). "For the MB49 bladder tumor model, the performance of VISTA mAb can effectively inhibit tumor growth by activating tumor-associated CD11c+DCs and inducing the production of IL-12 and TNF-α." (PMID 35831836, 2022). "In our study, TNF-α was implicated in mediating the OrfV-induced neutrophil cytotoxicity against tumor cells ex vivo." (PMID 36139433, 2022). "When FAP+ cells were depleted in lung or pancreatic cancers, it caused immediate growth arrest of immunogenic tumor through TNF-α- and IFN-γ-mediated mechanism." (PMID 35222418, 2022). "Tumor-associated macrophages release TNF-α to increase MMPs secreted by tumor cells and tumor stromal cells, destroy basement membrane tissue, and promote tumor metastasis." (PMID 34447750, 2021). "In response to TLR4 signaling in macrophages, the E2 mediated the secretion of inflammatory cytokine (IL-1β, IL-6, and TNF-α) and contributed to the tumor-associated inflammation and cancer immune escape." (PMID 34098945, 2021). "We have recently shown that intestinal epithelial ERβ in vivo protects from the epithelial damage caused by TNFα and prevents tumor formation." (PMID 33859619, 2021). "As a potent regulator of transcription and cell survival, TNFα has been implicated in the progression of multiple human cancers through promotion of tumor growth, angiogenesis, invasion and metastasis." (PMID 34650923, 2021). "Tumor-associated macrophages (TAMs) are responsible for the secretion of inflammatory cytokines such as tumor necrosis factor alpha (TNFα) which induces EMT via activation of p38 MAPK." (PMID 34220337, 2021). "TNFα, a proinflammatory cytokine that plays an important role in the microenvironment of tumors has been associated with tumor invasion and metastasis." (PMID 34764346, 2021). "For example, TNF-α can cause tumor-related endothelial cell apoptosis and tumor cell necrosis, and induce the expression of several immunomodulatory mediators." (PMID 34946640, 2021). "TNFα secreted by tumor-associated-macrophages has also been shown to induce EMT and stemness pathways via activation of NF-κB (Nuclear factor kappa-light-chain-enhancer of activated B cells)." (PMID 35582030, 2021). "The M2d subtype, also known as tumor‐associated macrophages (TAMs), secretes TNFα, IL‐6, IL‐10, TGFβ, and VEGFA to promote tumor progression." (PMID 34136188, 2021). "TNF-α is an important proinflammatory factor in the inflammatory microenvironment of a tumor, which can induce target cell DNA mutations, malignant cell proliferation, and neovascularization." (PMID 34194533, 2021). "Another study revealed that the loss of FXR increased the progression of tumour in mice model via Wnt signalling by increasing neutrophils, macrophages and TNF-α which lead to increased cell proliferation and decreased apoptosis." (PMID 35006466, 2021).